CTHRC1 (collagen triple helix repeat containing 1)
Diseases named in the same sentence as CTHRC1 in open-access papers (continued):
Sharing a sentence is not in itself a finding about the gene and the disease.
tumor (continued). "Taken together, these data suggest that CTHRC1 promotes tumor invasion by activating RhoA/ROCK pathway." (PMID 23922981, 2013). "The antibodies and Fab fragments were tested for recognition of native CTHRC1 and NFE2L3 proteins by immunoblotting analysis and enzyme-linked immunosorbent assay (ELISA) in colorectal cell lines derived from tumour and cancer tissues." (PMID 22321245, 2012). "Of these probe sets, several genes encoding proteins involved in extracellular matrix (ECM)-tumor interaction and focal adhesion (COL6A3, COL8A1, CTHRC1, THBS2, COMP) were upregulated, whereas ITGA2gene with the same function was downregulated in tumor cells." (PMID 17389037, 2007). "Furthermore, to ascertain the potential role of CTHRC1 in promoting tumor growth in ccRCC, we conducted animal experiments utilizing a nude mouse xenograft model." (PMID 41216505, 2026). "Moreover, CTHRC1 modulates the immunosuppressive tumor microenvironment of TNBC through the regulation of M2-type macrophages." (PMID 40134434, 2025). "Further clustering identified two distinct subpopulations within tumor-associated fibroblasts: CTHRC1-positive cells and negative cells." (PMID 40134434, 2025). "We further investigate the types of cells expressing CTHRC1, CST6, and AKR1B1 in tumor tissues, and the results indicate that CTHRC1, CST6, and AKR1B1 expression exhibits significant variability in GC, especially within key immune cell populations such as CD8 T cells, B cells, and DCs." (PMID 40978044, 2025). "Additionally, as the tumor T-stage and N-stage advanced, the expression of CTHRC1 exhibited an upward trend." (PMID 40134434, 2025). "Furthermore, we conducted sphere formation assays to investigate the regulatory role of CTHRC1 in CAFs on tumor stemness potential." (PMID 40751418, 2025). "We observed a strong association between CTHRC1 and tumor T-stage and N-stage specifically in TNBC, while no similar correlation was found in non-TNBC." (PMID 40134434, 2025). "CTHRC1 played a crucial role in the distinct tumour microenvironment of TNBC." (PMID 40134434, 2025). "Furthermore, additional analyses were performed to explore the relationship between CTHRC1, tumor immune cell infiltration, and immunotherapy in TNBC." (PMID 40134434, 2025). "Nevertheless, our study indicates that silencing CTHRC1 can robustly suppress tumor growth in vitro and in vivo, targeting CTHRC1 may be an effective strategy to treat ATC." (PMID 37273536, 2023). "Moreover, the current study is the first to report that upregulated CTHRC1 in tumor tissue is most likely secreted by fibroblasts in cancer stroma, which are mainly stellate cells and CAFs." (PMID 37444482, 2023). "This may be a complex result of gemcitabine’s cytotoxicity, and the anti-CTHRC1 antibody’s inhibition of tumor ECM production and facilitation of gemcitabine sensitivity through the inhibition of growth factors, such as HGF." (PMID 37444482, 2023). "CTHRC1 is overexpressed in multiple tumor types to promote tumor initiation and progression." (PMID 37938417, 2023). "CTHRC1 promotes tumor progression in both autocrine and paracrine manners; it stimulates cancer cell migration/invasion and proliferation directly, and also fuels tumor growth indirectly via tumor angiogenesis." (PMID 37444482, 2023). "However, in the orthotopic model, we discovered the unexpected differentiation of myCAFs to iCAFs in tumor tissues after a long-term (4-week) treatment with the anti-CTHRC1 antibody." (PMID 37444482, 2023). "Moreover, a substantial decrease in tumor volume and weight were observed in CTHRC1 knockdown group compared to the control group, indicating that CTHRC1 knockdown has a suppressive effect on ATC cell proliferation both in vitro and in vivo." (PMID 37273536, 2023). "The promoting effect of CTHRC1 on tumour metastasis and proliferation could be considered a contributing factor to its abnormal high expression in various cancers including COAD." (PMID 35300110, 2022).
tumor (continued). "Therefore, various tumour databases were used to investigate the expression of CTHRC1 in COAD at the mRNA and protein levels." (PMID 35300110, 2022). "In short, the tumour promoting mechanism of CTHRC1 involves multiple targets." (PMID 35300110, 2022). "Another concern is the mechanism of CTHRC1 in tumor angiogenesis." (PMID 35928443, 2022). "In addition, the expression of CTHRC1 was positively correlated with lymph node metastasis, tumor stage, and disease prognosis." (PMID 35307012, 2022). "In addition, overexpression of CTHRC1 contributes to tumorigenesis and progression through positive regulation of tumor spread, invasion, migration, adhesion, and metastasis." (PMID 36299502, 2022). "We found that CTHRC1 gene was highly expressed in 26 types of tumor (p < 0.05)." (PMID 35928443, 2022). "Moreover, CTHRC1 was highly expressed in at least 16 tumour types, which broadened the application of CTHRC1 in early disease detection." (PMID 35300110, 2022). "Cyclovirobuxine D (an alkaloid derived from Populus tremula) could inhibit EMT, proliferation, and invasion of tumor cells through the CTHRC1-AKT/ERK-Snail signaling pathway and exert anticancer effects." (PMID 35563653, 2022). "Collectively, these results indicate that CTHRC1 may be a key oncogene in multiple human tumors and closely related to the tumor stage." (PMID 34702252, 2021). "In addition, CTHRC1 coordinated the activity of ICP genes through diverse signal transduction pathways, was also associated with immune cell infiltration and the tumor microenvironment, and potentially represented a promising immunotherapy target." (PMID 34702252, 2021). "In addition, we have also explored the correlation between CTHRC1 expression and tumor purity in HNSC, KIRC, LIHC, LUAD, STAD, and UCEC using TIMER." (PMID 34615943, 2021). "Interestingly, we found that CTHRC1 methylation not only plays a procancer role but also functions as a tumor suppressor in some cancers." (PMID 34702252, 2021). "Additionally, CTHRC1 overexpression was significantly associated with different clinicopathological features, reduced OS duration, and CD8+ T immune infiltration and tumor purity." (PMID 34615943, 2021). "CTHRC1 serves as an essential factor in tumor development and a promising therapeutic target." (PMID 34702252, 2021). "Furthermore, we used the TIMER web resource and TISIDB database to analyze the correlation between CTHRC1 and tumor-infiltrated immune cells in the tumor microenvironment." (PMID 33628726, 2020). "CTHRC1 plays a pivotal role in some pathophysiological processes, including increasing bone mass, preventing myelination, and reversing collagen synthesis in many tumor cells." (PMID 32848510, 2020). "Besides, several recent studies have identified CTHRC1 as an effectual prognostic biomarker for predicting tumor recurrence or metastasis." (PMID 32848510, 2020). "In addition, we examined prognostic value of CTHRC1 level and tumor infiltrating immune cells in KIRP and KIRC, using Cox proportional hazard model by TIMER." (PMID 33628726, 2020). "As a participant in tissue remodeling or immune response in the tumor microenvironment, CTHRC1 may also participate in early-stage cancer." (PMID 32848510, 2020). "Additionally, CTHRC1 is positively related to different tumor-infiltrating immune cells in KIRP and KIRC." (PMID 33628726, 2020). "Therefore, CTHRC1 can participate in tumor cell migration and invasion through HIF-1α/CXCR4 signals in GC." (PMID 32848510, 2020). "CTHRC1 was previously reported to regulate tumor microenvironment." (PMID 33628726, 2020). "Besides, the use of CTHRC1 antibodies reduced tumor burden and TEMs infiltration in tumor tissue in xenograft mouse models." (PMID 33628726, 2020). "The CTHRC1 level correlates to tumor grade, stage, nodal metastasis, and worse survival prognosis." (PMID 33628726, 2020).
tumor (continued). "On the one hand, CTHRC1 changes the adhesion between cells by regulating the expression of molecules such as integrin β and MMPs, thereby enhancing cell mobility and promoting tumor metastasis and invasion." (PMID 32848510, 2020). "Moreover, overexpression of miR-155 can silence downstream CTHRC1, thereby inhibiting cell proliferation and inducing apoptosis of cells to prevent tumor progression and metastasis." (PMID 32848510, 2020). "However, the specific functional mechanism in this study remains to be studied, and we will further explore the potential mechanism between CTHRC1 expression and tumor angiogenesis in LUAD in our next study." (PMID 31798347, 2019). "However, the relationship between CTHRC1 expression and tumor angiogenesis and tumor microenvironment in LUAD is still unclear." (PMID 31798347, 2019). "Additionally, CTHRC1 overexpression increased the ability of tumour cells to invade through a Transwell gel, and CTHRC1 depletion suppressed tumour cell invasion." (PMID 29631554, 2018). "Furthermore, tumour cell migration speed increased with CTHRC1 overexpression but was inhibited with CTHRC1 depletion." (PMID 29631554, 2018). "Moreover, we demonstrated that CTHRC1 promoted tumour invasion by regulating MMP7 and MMP9 expression, which is mediated by the AP-1/c-Jun and NF-κB pathways, respectively." (PMID 29631554, 2018). "Additionally, serum concentration of CTHRC1 correlates with metastasis, clinical stage and circulating tumour cell (CTC) number and functions as an important prognostic factor for NSCLC patients." (PMID 29631554, 2018). "According to our Transwell results, CTHRC1 overexpression increased tumour invasion." (PMID 29631554, 2018). "Another mechanism by which CTHRC1 promotes tumor invasion and metastasis may be related to EMT progression." (PMID 29285247, 2017). "Collectively, we speculated that HCCLM3 cells secreted CTHRC1 into the tumor microenvironment by down-regulating miR-155-5p and then attenuated cancer cell growth and metastasis by activating GSK-3β-involved Wnt/β-catenin signaling." (PMID 29234238, 2017). "CTHRC1 protein expression was determined by immunoblot analysis in 12 HCC/non-tumor tissue pairs." (PMID 29285247, 2017). "Pyrosequencing was performed for further validation, and as expected, cg07757887 methylation was significantly lower in ESCC tumour tissues compared with corresponding non-tumour tissues (n = 50, P < 0.0001, t-test), with 92% (46/50) of tumour tissues showing CTHRC1 hypomethylation." (PMID 28645305, 2017). "Interestingly, our results show a correlation between the expression of CTHRC1 and tumor grade in TUR samples, and the most aggressive of the three cell lines included in this study, J82, also expressed high transcription level of CTHRC1 gene." (PMID 28427201, 2017). "Immunohistochemistry confirmed markedly high CTHRC1 protein expression in tumour tissues, and high CTHRC1 expression was positively correlated with advanced T stage (P = 0.043), lymph node metastasis (P = 0.023), TNM stage (P = 0.024) and poor overall survival (P = 0.020)." (PMID 28645305, 2017). "Our results showed that the mRNA levels of the CTHRC1 gene were decreased after treatment with sera from patients with spontaneous regression of malignant disease with high titres of anti‐CA I autoantibodies in all four tested tumour cell lines." (PMID 27704726, 2017). "Additionally, tumor weight in the CTHRC1 group was greater than that in the NC group, and tumor weight was significantly decreased in the miR-155-5p group when compared to the NC group (p = 0.04, 0.03, 0.02, respectively)." (PMID 29234238, 2017). "We therefore examined whether CTHRC1 overexpression was involved in tumor invasiveness and metastasis by changing the EMT phenomena in HCC cells." (PMID 29285247, 2017).
tumor (continued). "Moreover, elevated miR-155-5p expression promoted apoptosis but suppressed cell cycle progression and cell proliferation, invasion and migration in vitro and facilitated tumor formation in vivo; elevated CTHRC1 expression abolished these biological effects." (PMID 29234238, 2017). "Finally, a xenograft model of BALB/c nude mice was established to certify the impacts of miR-155-5p and CTHRC1 on tumor formation in vivo." (PMID 29234238, 2017). "On the other hand, the decreased levels of mRNAs encoding type I collagen, type IV collagen, laminin subunit gamma 2 and two proto oncogenes WNT7B and CTHRC1, suggest a complex and profound effect of the sera of patients with spontaneous tumour regression on the cancer cells." (PMID 27704726, 2017). "In addition, an immunofluorescence analysis demonstrated substantially reduced blood vessel density in xenograft tumor tissues from mice injected with the CTHRC1-neutralizing antibody." (PMID 27686285, 2016). "Moreover, rCTHRC1 upregulated angiopoietin-2 (Ang-2), a Tie2 receptor ligand, through ERK-dependent activation of AP-1 in ECs, resulting in recruitment of Tie2-expressing monocytes (TEMs) to CTHRC1-overexpressing tumor tissues." (PMID 27686285, 2016). "Moreover, elevated levels of Ang-2 facilitated infiltration of TEMs into CTHRC1-overexpressing tumor tissues." (PMID 27686285, 2016). "Moreover, administration of a CTHRC1-neutralizing antibody to a xenograft mouse model reduced the tumor burden and infiltration of TEMs in the tumor tissues, indicating that blocking the CTHRC1/Ang-2/TEM axis during angiogenesis inhibits tumorigenesis." (PMID 27686285, 2016). "In the recent study of solid tumors, it was shown that CTHRC1 is produced by a tumor stroma." (PMID 27430622, 2016). "Although CTHRC1 secretion affects tumor cells, how it promotes tumorigenesis in the context of the microenvironment is largely unknown." (PMID 27686285, 2016). "In those results, CTHRC1 could be expressed in normal cells and tissues, but also high expression in tumor cells and tissues." (PMID 24504172, 2014). "CTHRC1 was detectable in normal tissues, but also was highly expressed in tumor specimens." (PMID 24504172, 2014). "Occasionally white adipocytes adjacent to the tumor also expressed Cthrc1." (PMID 24945147, 2014). "In the modified Boyden chamber assay, knockdown of CTHRC1 dramatically inhibited tumor invasion." (PMID 23922981, 2013). "On the other hand, overexpression of CTHRC1 promoted tumor invasion." (PMID 23922981, 2013). "Since CTHRC1 overexpression in HCC is associated with advanced stage, we speculated that CTHRC1 may play a role in tumor growth and invasion." (PMID 23922981, 2013). "Additionally, CTHRC1's roles extend to the regulation of hypoxia-related pathways, metabolism of glycolysis and fatty acids, and involvement in tumor angiogenesis, all of which support tumor immune evasion." (PMID 40201173, 2025). "Finally, although we found that anti-CTHRC1 treatments significantly suppressed tumor growth in the mice models, whether the shift of myCAFs to iCAFs has anti-tumor effects or influences survival should be studied." (PMID 37444482, 2023). "Moreover, it is considered that CTHRC1 could promote early-stage cancer and is a candidate as a prognostic biomarker, signaling tumor recurrence or metastasis." (PMID 35328635, 2022). "The results showed that the high expression of CTHRC1 was enriched in various pathways and key biological functions, and was related to the occurrence of tumors, such as Gα signaling, GPCR ligand binding, neutrophil degranulation, interleukin signaling, and tumor-associated pathways." (PMID 35307012, 2022).
tumor (continued). "Moreover, we have also found that CTHRC1 expression was inversely correlated with tumor purity in HNSC, KIRC, LIHC, LUAD, STAD, and UCEC, this knowledge may also help in predicting the clinical outcomes in HNSC, KIRC, LIHC, LUAD, STAD, and UCEC." (PMID 34615943, 2021). "Thus, CTHRC1 plays a vital role in the fields of human tumor." (PMID 33102569, 2020). "Therefore, PKC-δ signal may explain the role of CTHRC1 in tumor progressions such as angiogenesis and bone metastasis." (PMID 32848510, 2020). "Therefore, CTHRC1 may be a potential target in combination with antitumor drugs in the future, which can promote the research progress of tumor-targeted drugs." (PMID 32848510, 2020). "However, the underlying mechanisms of CTHRC1 in KIRP and KIRC progression and tumor-infiltrating lymphocytes remains unclear." (PMID 33628726, 2020). "Thus, CTHRC1 has multifaceted functions in the tumor microenvironment." (PMID 33628726, 2020). "However, the association of CTHRC1 with the prognosis and tumor-infiltrating lymphocytes of KIRP and KIRC has not been reported." (PMID 33628726, 2020). "Therefore, CTHRC1, a candidate tumor marker, may be a potential metastasis-related gene in myelocytomas caused by ALV-J." (PMID 33102569, 2020). "Indeed, this anti-fibrotic agent induces apoptotic cell death of CAFs residing among NSCLC cells and decreases the expression of collagen triple helix repeat containing 1 (CTHRC1), which is associated with tumor aggressiveness and poor clinical outcomes for NSCLC patients." (PMID 31067787, 2019). "Additionally, CTHRC1 increases tumour cell migration and invasion in vitro." (PMID 29631554, 2018). "In addition, CTHRC1 may have other functions in tumor microenvironment, like microenvironment remodeling or immune response, etc." (PMID 28303973, 2017). "TGF-β1 inhibitor SB431542 efficiently suppressed CTHRC1 expression and inhibited activations of their downstream molecules, implicating that growth factors may be responsible for CTHRC1 expression and subsequent tumor invasion and metastasis." (PMID 29285247, 2017). "Because CTHRC1 is known to have a role in vascular remodeling through matrix deposition and cell migration in injured tissues, we proposed that CTHRC1 may be a novel paracrine factor in the regulation of neovasculogenesis in the tumor microenvironment." (PMID 27686285, 2016). "Furthermore, because CTHRC1 is a secreted protein, it may function as a paracrine factor in the tumor microenvironment, promoting the migration and invasion of many cell types regardless of the cell-type that has produced it." (PMID 26918341, 2016). "Besides, the functional role of CTHRC1 in cancer cell migration and adhesion suggests that blocking CTHRC1, such with neutralizing antibody, may inhibit tumor metastasis and therefore be therapeutically beneficial." (PMID 23922981, 2013). "Since CTHRC1 is a secretory protein highly expressed in cancers, it is likely to be aberrantly expressed in the serum of cancer patients and may be considered a promising tumor marker." (PMID 23922981, 2013). "Promoter hypomethylation in tumor tissues correlated with overexpression of LAMC2, CTHRC1, CXCL13, FST, SPP1, and PLAU, whereas CDKN2A showed hypermethylation." (PMID 41776121, 2026). "Crucially, in vitro validation confirms that CTHRC1+ CAFs secrete WNT5A, which upregulates the mesothelin (MSLN) gene in CRC tumor cells - an effect abolished by WNT5A inhibition or CTHRC1 knockdown." (PMID 41450739, 2025). "With statistically significant differences, CTHRC1, CST6, and AKR1B1 were highly expressed in the tumor and lowly expressed in the normal in both paired and unpaired samples of patients with GC (p < 0.05)." (PMID 40978044, 2025). "In addition, CTHRC1 may indeed play a functional role in shaping the tumor immune microenvironment." (PMID 40978044, 2025). "CTHRC1 and ANO3 were shown to be highly expressed in metastatic tumours compared to primary tumours." (PMID 39748426, 2025).